AHNAK2 (AHNAK nucleoprotein 2)
Diseases named in the same sentence as AHNAK2 in open-access papers (continued):
Sharing a sentence is not in itself a finding about the gene and the disease.
cancer (continued). "In recent years, based on bioinformatics analysis, AHNAK2 has been reported to be involved in the carcinogenesis of a variety of cancers, especially adenocarcinomas." (PMID 36017889, 2022). "Little work has been done in exploring the function and relation AHNAK2 has with cancer, with early studies showing promising potential as a future biomarker and therapeutic target." (PMID 35158796, 2022). "In our research, NDC80, NPAS2, and AHNAK2 were sifted out from the ISGs family to develop a signature that improved the prediction of OS for pan-cancer patients." (PMID 35813478, 2022). "AHNAK2 was found to be mostly localised in the cytoplasm and plasma membrane of the epithelial cancer cells." (PMID 35158796, 2022). "Then, we retrospectively evaluated associations between the two AHNAK2 expression patterns and the prognoses in terms of recurrence-free survival (RFS) and cancer-specific survival (CSS)." (PMID 33918555, 2021). "Statistical analyses were performed to compare associations between the two AHNAK2 expression patterns and the prognoses in terms of recurrence-free survival (RFS) and cancer-specific survival (CSS)." (PMID 33918555, 2021). "As shown in the bar chart and circle graph, AHNAK2 was significantly associated with the pathway of focal adhesion, ECM-receptor interaction, and proteoglycans in cancer." (PMID 32904605, 2020). "Gene Expression Profiling Interactive Analysis (GEPIA) showed that AHNAK2 expression status varies in different cancers." (PMID 32966238, 2020). "AHNAK2 is an extremely significant gene in the survival statistics of a large number of pan-cancer samples (N = 9497, HR = 1.4, P<0.0001)." (PMID 32966238, 2020). "AHNAK2 expression is significantly high in patients with an advanced cancer stage, an advanced T classification, lymph node metastasis, and increased BRAF mutations, showing a positive correlation with PTC progression." (PMID 32966238, 2020). "Research on the cancer candidate gene AHNAK2 will help us understand the development and prognosis of cancer and provide a piece of the puzzle to overcome cancer." (PMID 32966238, 2020). "First, we investigated the expression and prognostic value of the AHNAK2 gene in cancer." (PMID 41465903, 2025). "Further studies are needed to decrypt the effect of AHNAK2 in cancer immunotherapy." (PMID 35359393, 2022). "It has previously been observed that AHNAK2 is overexpressed in many cancers and acts as a poor prognostic biomarker in clear cell renal cell carcinoma (ccRCC), pancreatic ductal carcinoma (PDAC), papillary thyroid carcinoma (PTC), and lung adenocarcinoma (LUAD)." (PMID 35359393, 2022). "This study also provides strong support for AHNAK2 as a prognostic biomarker for pan-cancer." (PMID 32966238, 2020). "To investigate whether AHNAK2 has broad value, we performed a series of studies on AHNAK2 across all cancers." (PMID 32966238, 2020). "Although the biological function of AHNAK2 in cancer remains unclear, some progress has been made regarding its mechanism in tumors." (PMID 32966238, 2020). "The results of immunohistochemistry in CP tissues showed decreased expression of AHNAK2, indicating that AHNAK2 could be used in the differential diagnosis when a CP patient has suspected cancer." (PMID 28423668, 2017). "They found that patients with high AHNAK2 expression had significantly lower recurrence-free survival (RFS) and cancer-specific survival (CSS)." (PMID 38033502, 2023). "The other 6 genes, GPR98, ZFYVE26, AHNAK2, APOB, ZNF236, and ODZ1, were all supported to be related to cancers by research." (PMID 33244318, 2020). "All three cancer cell lines with AHNAK2 knockdown or non-targeting siRNA controls, were co-cultured individually with pancreatic stellate cells (PS1)." (PMID 39849106, 2025). "Immunohistochemistry of 14 samples of resected human PDAC showed protein expression in cancer cells, with adjacent normal pancreas demonstrating no expression of AHNAK2." (PMID 39849106, 2025).
cancer (continued). "Finally, the enhanced crosslinking and immunoprecipitation (eCLIP) analyses reveal that FXR1 binds with the G4-enriched mRNA targets such as AHNAK, MAP1B, AHNAK2, HUWE1, DYNC1H1 and UBR4 and controls its mRNA expression in cancer cells." (PMID 38709899, 2024). "From the list of 20 FLAGS (FrequentLy mutAted GeneS) genes that are known to be frequently mutated in cancer but are unlikely to be pathogenic, TTN, AHNAK2, SYNE1, MUC16, and OBSCN were found among genes altered at ≥ 20% in mCLM." (PMID 38008721, 2023). "reveal that the overexpression of AHNAK2 could drive tumorigenesis and progression of ccRCC by facilitate EMT and cancer cell stemness." (PMID 37377953, 2023). "An in vivo study of various cancers, including prostate (DU145), lung (H460), breast (MCF-7), and renal (CAKI-1) cancer cell lines and normal (293T) cells, provided evidence that AHNAK2 expression increased gradually in a hypoxic growth environment (1% O2) in comparison to normoxia (21% O2)." (PMID 35158796, 2022). "AHNAK2 was not expressed in cystitis, showed only marked expression in low-grade cancer, and had a high level in high-grade cancer." (PMID 35330118, 2022). "Genes such FAM182A, SOX9, AHNAK2, ENSG00000121031, FLT3LG, PMEPA1, ZFP36L2 in the large intestine, ALB, KRTAP19-1, APOB, CD200, CRYGD, KRTAP24-1, OR6N2 in the liver are novel predictions, and their functions in these cancers can further be studied." (PMID 34997044, 2022). "The GSEA results also revealed that AHNAK2 may promote progression in PTC through cell adhesion-, cell junction-, immune-, and cancer-related pathways." (PMID 32966238, 2020). "A study showed that multiple sites in the CRU region of AHNAK2 could be methylated by SMYD2, thus participating in the regulation of cell adhesion, cancer cell migration, and invasion." (PMID 32904605, 2020). "AHNAK2 has also been reported to be involved in human esophageal squamous carcinoma (ESCC) by regulating protein lysine mono-methyltransferase SMYD2, which is overexpressed or amplified in various types of cancers." (PMID 28423668, 2017). "We also determined whether AHNAK2 expression has more prognostic value in advanced cancers or not." (PMID 28423668, 2017). "However, AHNAK2 was never been confirmed as a cancer biomarker until Manoj reported that AHNAK2, together with other 4 proteins, could help diagnose PDAC with high sensitivity and specificity; however, there was no tissue-based evidence in that study." (PMID 28423668, 2017). "No details about AHNAK2 function are available, but its closest relative AHNAK is involved in cancer migration and EMT, providing support that AHNAK2 may elicit similar features." (PMID 26993610, 2016).
adenocarcinoma (3 papers, 2022 to 2026). A common cancer characterized by the presence of malignant glandular cells. "The prevalent nature of AHNAK2 in glandular tissue provides the potential opportunity to use AHNAK2 neoantigens as a target for multisystem adenocarcinomas." (PMID 41471728, 2025). "In conclusion, our study demonstrated that AHNAK2 is a biomarker of adenocarcinoma, and it is urgent to further explore its function and the underlying mechanism in the future." (PMID 36017889, 2022). "It was found that the expression of AHNAK2 was significantly higher in these adenocarcinomas than in normal gland tissues." (PMID 36017889, 2022). "The immunohistochemical results of our study showed that the localization of AHNAK2 is mainly in the cytoplasm of adenocarcinoma cells." (PMID 36017889, 2022). "Taken together, these data demonstrated that AHNAK2 is a potential biomarker for various adenocarcinomas." (PMID 36017889, 2022). "Our study demonstrated that AHNAK2 is a novel biomarker of adenocarcinomas, and has the potential to become a target for the treatment of adenocarcinomas." (PMID 36017889, 2022). "Together, these results demonstrated that AHNAK2 is critical for the progression and metastasis of adenocarcinomas." (PMID 36017889, 2022). "Together, we demonstrate that AHNAK2 is a biomarker and a potential therapeutic target for adenocarcinomas." (PMID 36017889, 2022). "We described AHNAK2 as a biomarker and therapeutic target for adenocarcinomas." (PMID 36017889, 2022). "Therefore, AHNAK2 can be used as a biomarker for adenocarcinomas." (PMID 36017889, 2022). "Interestingly, it was further found that AHNAK2 was not expressed in a variety of normal glandular epithelium, but highly expressed in a variety of corresponding adenocarcinomas, such as the esophagus, breast, and colon." (PMID 36017889, 2022).
cardiac disease (1 paper, 2023). "As its homologue, does AHNAK2 influence the development of cardiac disease by regulating L-type calcium channels?" (PMID 38033502, 2023).
AHNAK2 also shares sentences with these, for which no sentence is quoted: glioblastoma (5 papers); autoimmune disease (2); cervical cancer (2); colorectal cancer (2); non-small cell lung carcinoma (2); Salmonella Infections (2); Alzheimer disease (1); atherosclerosis (1); atrial fibrillation (1); autoimmune disorders (1); basal cell carcinoma (1); benign bladder tumors (1); breast invasive carcinoma (1); carcinoma in situ (1); cervical squamous cell carcinoma (1); colon cancer (1); COVID-19 (1); diabetes (1); Duchenne muscular dystrophy (1); escherichia coli infection (1); esophageal adenocarcinoma (1); esophageal squamous cell carcinoma (1); gallbladder carcinoma (1); head and neck squamous cell carcinoma (1); Impaired glucose tolerance (1); mesothelioma (1); ovarian serous cystadenocarcinoma (1); pancreatic adenocarcinoma (1); Parkinson disease (1); periodontitis (1).
A further 9 diseases each share a sentence with AHNAK2 in 1 paper.